IGFBP2 (insulin like growth factor binding protein 2)
Diseases named in the same sentence as IGFBP2 in open-access papers (continued):
Sharing a sentence is not in itself a finding about the gene and the disease.
Stroke (continued). "Therefore, the objective of this study was to determine how ischemic injury may effect IGFBP-2 protein levels in the mouse brain, particularly in the stroke penumbra, the main target of neuroprotective treatments." (PMID 24359611, 2013). "In addition to these, certain other IGF binding proteins are evidently influenced by hormone therapy and may be related to CHD (IGFBP1) or stroke (IGFBP2, IGFBP6)." (PMID 20667078, 2010). "Another region specific change of protein levels occurs in the stroke core where a significant increase of IGF-I and IGFBP-2 levels is observed." (PMID 24359611, 2013). "The possibility for transportation is supported by our finding that IGFBP-2 and IGF-I distribution changes after stroke." (PMID 24359611, 2013). "In models of both seizure and stroke, reactive astrocytes upregulated both P2Y1R and IGFBP2; this may be a common functional phenotype of reactive astrocytes in both disease models." (PMID 39117630, 2024). "IGFBP2 is co-upregulated with P2Y1R in reactive astrocytes in seizure and stroke models." (PMID 39117630, 2024). "In addition, several physiological conditions such as fasting, stroke, and hypoxia enhanced IGFBP-2 levels and IGFBP-2 locally expressed in the CNS." (PMID 31824433, 2019). "Insulin-like growth factor binding protein-2 (IGFBP-2) regulates the bioavailability, transportation, and localization of insulin-like growth factor-I (IGF-I), an effective neuroprotectant in animal stroke models especially when administered intranasally." (PMID 24359611, 2013). "However, no direct link has been established for IGFBP-2′s transport function of IGF-I into the stroke penumbra." (PMID 24359611, 2013). "Such an increase in IGF-I levels in the stroke penumbra further supports the hypothesis that IGF-I is an integral part of the brain’s endogenous response to hypoxic-ischemic brain injury and that IGFBP-2 also has a function in this response." (PMID 24359611, 2013).
acute kidney injury (6 papers, 2018 to 2025). Sudden and sustained deterioration of the kidney function characterized by decreased glomerular filtration rate, increased serum creatinine or oliguria. "Studies on male rats with acute kidney injury have shown high expression of IGFBP-2 in their renal tissues." (PMID 40231291, 2025). "Studies on male rats with acute kidney injury showed high IGFBP-2 protein expression in their renal tissues." (PMID 38137505, 2023). "The authors found that urinary TIMP2 × IGFBP-2 is an early predictor of acute kidney injury and increased precociously in acute septic kidney injury after cardiac surgery." (PMID 38137505, 2023). "In male acute kidney injury rat models, the IGFBP-2 protein is highly expressed in kidney tissues." (PMID 40231291, 2025). "Increased circulating IGFBP2 may be a predictor of the longitudinal deterioration of renal function in a variety of kidney diseases, including acute kidney injury." (PMID 36008635, 2022). "RT-qPCR validated miRNA and mRNAs included IGFBP2 (respiratory system); MMP9 and PDE4B (nervous system); PPARG (cardiovascular system); AKR1B1, ANXA1, and LNC2/NGAL (acute kidney injury); GFER/ALR (liver); and miR-30c-3p (coagulopathy)." (PMID 34573990, 2021). "However, since the current literature indicates that IGFBP-2 may play a role in kidney diseases and targeting, to find an early marker for renal insufficiency in septic patients, IGFBP-2 should be further investigated in larger cohorts of septic patients with renal failure." (PMID 38137505, 2023).
astrocytoma (6 papers, 2007 to 2025). "IGFBP2 protein expression was low or undetectable in lower-grade (G.2 and G.3) astrocytoma samples." (PMID 41366031, 2025). "FeaturePlots confirmed upregulation of select ECM glycoprotein genes, including IGFBP2 and MGP, in the GBM sample versus grade III astrocytoma." (PMID 41366031, 2025). "MMP‐9 has been shown to induce IGF‐2/IGFBP2 complex proteolysis resulting in the extracellular release of free IGF‐1 with positive and biological effect on astrocytoma cellular growth and migration." (PMID 29321953, 2018).
endometrial cancer (6 papers, 2018 to 2025). Primary or metastatic malignant neoplasm involving the endometrium (mucous membrane that lines the endometrial cavity). "Both the mTOR inhibitor RAD001 and the AKT inhibitor terameprocol (M4N) downregulated IGFBP2 expression in endometrial cancer cells by targeting the Sp1 transcription factor, resulting in synergistic inhibition of tumor growth." (PMID 40746599, 2025). "Insulin-like growth factor binding protein 2(IGFBP2) is overexpressed in endometrial cancer tissue and acted through the PI3K/AKT/mTOR pathway." (PMID 40746599, 2025). "Furthermore, the combination of terameprocol and everolimus (RAD001) significantly reduced insulin-like growth factor binding protein 2 (IGFBP-2) overexpression and synergistically suppressed endometrial cancer growth." (PMID 36771042, 2023). "In a model of endometrial cancer where IGFBP-2 overexpression correlates with disease progression, hypoxic environments significantly mediate IGFBP-2 overexpression and allow HIF-1α to bind to its promoter." (PMID 41226289, 2025). "We observed that derepression of let-7 targets was the strongest GSEA signature obtained in DICER1 endometrial cancer, with known let-7 oncogene targets HMGA2 and IGFBP2 strongly deregulated." (PMID 31417090, 2019).
esophageal adenocarcinoma (6 papers, 2015 to 2021). A malignant tumor with glandular differentiation arising predominantly from Barrett mucosa in the lower third of the esophagus. "In esophageal adenocarcinoma, treatment-resistant patients display high expression levels of IGFBP2 as compared to chemo-naive patients." (PMID 33673232, 2021). "Studies conducted on oesophageal adenocarcinoma cells have also indicated that IGFBP-2 modulates the response of cells to chemotherapy." (PMID 29088813, 2017). "In esophageal cancer, IGFBP2 overexpression is associated with shorter disease-free intervals and treatment resistance, and the knockdown of IGFBP2 sensitizes esophageal adenocarcinoma cells to cisplatin in a serum-dependent manner." (PMID 28903396, 2017). "Significantly, simultaneous IGFBP2 depletion and pharmacological inhibition of Akt and MAPK pathways sensitized esophageal adenocarcinoma cells to cisplatin therapy." (PMID 33673232, 2021). "Normal esophageal squamous epithelia (NE) and Barrett’s esophagus (BE) showed negative or weak immunostaining for IGFBP2." (PMID 30626422, 2019).
fibrosis (6 papers, 2022 to 2025). the formation of excess fibrous connective tissue in an organ or tissue in a reparative or reactive process. "Serum IGFBP-2 levels were notably increased in patients with chronic hepatitis C, especially in advanced fibrosis and cirrhosis." (PMID 38137505, 2023). "IGFBP-2 was increased in all MCD-fed mice compared with the controls; according to fibrosis, F0 exhibited the highest expression in the hepatic tissue, and it decreased in F1C and F2." (PMID 38541155, 2024). "In a previous study, it was found that the circulating level of IGFBP2 was elevated specifically in F4 stage fibrosis patients with chronic hepatitis C (CHC) but showed no significant changes in F0–F3 stages." (PMID 40608848, 2025). "Additionally, studies report IGFBP2, through the STAT3 pathway, induces lung fibrosis and inflammation in rats with severe pneumonia." (PMID 38918843, 2024). "Here, we observed an increase in IGFBP-2 during NAFLD and fibrosis in both the liver and serum." (PMID 38541155, 2024). "IGFBP2 promotes ERK phosphorylation in an integrin-dependent manner, which could link it to atrial fibrosis and AF pathogenesis via cellular signaling pathways." (PMID 37435047, 2023).
liver disease (6 papers, 2011 to 2026). "This epigenetic inhibition of Igfbp2 becomes stable over time in adult mice, suggesting Igfbp2 methylation as a predictable risk indicator of liver disease development." (PMID 33193730, 2020). "B2M, CEA, GDF15, IGFBP2, OPN and PDGF-Rb, which are uncertain about the association with liver cancer but have involvement in liver diseases or multiple cancers; 3)." (PMID 30220970, 2018). "Biomarkers previously associated with liver diseases and identified in our samples were among others: ANGPTL3, IGFBP2, SDC4, IL1RN." (PMID 21978410, 2011).
neuroblastoma (6 papers, 2014 to 2025). Neuroblastoma (NB) is the most common solid, extracranial childhood tumor. "Previous data from our laboratory have shown that sAPPα up-regulates the transcripts of IGF2 and IGFBP2 transiently after 30 min exposure in a human neuroblastoma SH-SY5Y cell culture model." (PMID 37108327, 2023). "Furthermore, IGFBP‐2 directly activates the VEGF gene promoter, upregulating VEGF expression and facilitating angiogenesis in neuroblastoma cells." (PMID 40232500, 2025).
non-alcoholic fatty liver disease (6 papers, 2020 to 2026). "In humans, IGFBP2 serum concentration was lower in obese men with non-alcoholic fatty liver disease (NAFLD) and steatohepatitis (NASH) compared to non-obese controls, and liver fat reduction by weight-loss intervention correlated with an increase of IGFBP2 serum levels." (PMID 32532003, 2020).
ovarian tumors (6 papers, 1996 to 2025). "For example, IGFBP-2 induction has been shown to activate cell invasion, and increased levels of IGFBP-2 have been reported in ovarian tumour tissues and serum, as well as increased IGFBP-3 mRNA expression in HNSCC compared to healthy tissue." (PMID 28143425, 2017). "Southern blot analysis revealed no amplification of IGFBP-2 gene in the DNA samples from ovarian tumours regardless of their nature." (PMID 8624265, 1996).
steatosis (6 papers, 2020 to 2025). Increased lipid within the cytoplasm of cells. "An integrated bioinformatics and experimental study found that hepatic IGFBP2 expression was inversely associated with steatosis and serum ALT/AST levels." (PMID 40608848, 2025). "These inherited anti‐Lepr miRNAs, also referred to inherited anti‐Lepr miRNAs (IAL‐miRs), modulate hepatic steatosis, and insulin signaling through the Lepr regulatory Igfbp2, Egfr, and Ampk." (PMID 39792613, 2025). "Reduction of IGFBP2 was associated with a lower NAS score (r = 0.35, p = 0.02) and hepatocellular ballooning grade (r = 0.37, p = 0.02), but not with changes in the lobular inflammation grade (r = 0.17, p = 0.28) or steatosis grade (r = 0.17, p = 0.28)." (PMID 36831184, 2023). "Of the top-ranked 10 genes, two genes (CYP7A1 and PEG10) were significantly up-regulated in both steatosis and NASH patients, while eight genes (FOSB, FOS, IL6, GADD45G, MYC, SLITRK3, JUNB, and IGFBP2) were significantly down-regulated." (PMID 33324350, 2020). "In addition to steatosis, paternal exposure to BPA led to a decrease in expression of Lepr, Igfbp2, and pAmpk, and upregulation of Srebf1 and Pparg in the liver of both male and female offspring." (PMID 39792613, 2025). "Analyses of these proteins showed a negative correlation between IGFBP2, IGFBP4, and steatosis grade (r = −0.49, p < 0.02; r = −0.12, p < 0.02), while IGFBP6 and IGFBP7 were positively associated with steatosis (r = 0.25, p < 0.005; r = 0.35, p < 0.0001)." (PMID 36831184, 2023).
adenoma (5 papers, 2006 to 2022). A neoplasm arising from the epithelium. "In accordance with this, in our studies one animal showed tremendously increased IGFBP-2 levels at a later stage that correlated well with its very poor status because of development of several large adenomas spreading over the middle and distal colon." (PMID 17118177, 2006). "The genes CDH3, ECM1, IGFBP2, and MET, which are associated with cell adhesion, the extracellular matrix, and cancer cell invasion/metastasis, are also observed frequently increased in these two adenoma samples." (PMID 27100181, 2016). "Indeed, overexpression of Igfbp2 in transgenic mice led to decreased appearance of dysplastic aberrant crypt foci and inhibited the growth of adenomas." (PMID 19812696, 2009). "In IGFBP-2 transgenic mice which overexpress IGFBP-2, CRC incidence was similar to that of the control group of animals, but the volume of adenomas was more than two times smaller." (PMID 36013453, 2022).
breast tumors (5 papers, 2011 to 2023). "To assess the effect of IGFBP2 reintroduction on the breast tumor microenvironment, we co-xenografted MM231s with the IGFBP2- or mT2-overexpressing TIFs." (PMID 37436978, 2023). "Another important finding from our data is the correlation of IGFBP2 over expression with elevated β-catenin levels in breast tumors." (PMID 23767917, 2013). "Immunohistochemical and immunocytochemical staining was performed on breast tumors and experimental cells, respectively for β-catenin and IGFBP2 expression." (PMID 23767917, 2013). "In humans, breast tumors frequently exhibit elevated levels of IGFBP2 and β-catenin, with higher expression levels of β-catenin correlating with a decreased patient survival." (PMID 23767917, 2013). "Transcriptome analysis of breast tumor cells (BT474) with stable knockdown of IGFBP2 and breast tumors having differential expression of IGFBP2 by immunohistochemistry was performed using microarray." (PMID 23767917, 2013). "Initially, stable sub lines of breast tumor cell line BT474 with knockdown of IGFBP2 were generated." (PMID 23767917, 2013). "Furthermore, IGFBP2 and β-catenin are co-ordinately overexpressed in breast tumors and correlate with lymph node metastasis." (PMID 23767917, 2013). "IGF1 was expressed in 30% of breast tumors, IGF1R in 26%, IGFBP2 in 74%, and IGFBP3 in 32%." (PMID 25619494, 2015). "In vivo, metastatic human breast tumors had higher levels of MMP-2 than did non-metastatic tumor tissue, whereas adipocytes around metastatic breast tumors had higher levels of IGFBP-2 than did adipocytes surrounding non-metastatic breast tumors." (PMID 25747684, 2015). "Whole genome expression analysis of breast tumors with or without IGFBP2 expression indicated changes in genes belonging to Focal adhesion, Map kinase and Wnt signaling pathways." (PMID 23767917, 2013). "Indeed, scatter plots show that mRNA levels of IGFBP2 and SPIB, the two most differentially regulated genes, were significantly different between NIS-negative (0+) versus NIS-positive (3+) breast tumors." (PMID 21989294, 2011). "In addition, since Wnt pathway genes were significantly regulated in IGFBP2 knock down cells, we studied the expression of Wnt target genes in IGFBP2 positive and negative breast tumors." (PMID 23767917, 2013).
Cirrhosis (5 papers, 2022 to 2025). A chronic disorder of the liver in which liver tissue becomes scarred and is partially replaced by regenerative nodules and fibrotic tissue resulting in loss of liver function. "IGFBP2 has recently been identified to be the second-most differentially regulated protein in the progression from MAFLD to cirrhosis in an Icelandic population." (PMID 39202457, 2024). "IGFBP2 levels were elevated in individuals with cirrhosis but reduced in NAFL compared with population controls." (PMID 36280732, 2022). "The association of IGFBP2 and IGFBP7 with cirrhosis and NAFL is consistent with previous studies of NASH progression." (PMID 36280732, 2022). "IGFBP2 was elevated in cirrhosis but reduced in NAFLD compared to the general population." (PMID 40004054, 2025). "Key findings included increased IGFBP2 and THBS2 levels in cirrhosis compared to NAFLD and the general population, while ACY1 levels were higher in NAFLD in contrast to the general population." (PMID 40004054, 2025). "Additional studies are needed to understand the interactions between FOG2S657G, IGFBP2, and mechanisms of progression from MAFLD to cirrhosis." (PMID 39202457, 2024).
diabetic nephropathy (5 papers, 2012 to 2025). "The cellular activities of IGFBP2 in the kidney may have significant implications in diabetic nephropathy and research is required to elucidate whether there is a causative relationship between circulating IGFBP2 and progression of renal disease." (PMID 23781310, 2012). "Proinflammatory and proapoptotic effects were reported in diabetic kidney disease, while in cancer IGFBP2 can induce M2 macrophage polarization." (PMID 39234304, 2024). "IGF-binding protein 2 (IGFBP2) and IGF2 are expressed in the kidney, but their associations with diabetic nephropathy are unclear." (PMID 23781310, 2012).
esophageal cancer (5 papers, 2015 to 2024). A primary or metastatic malignant neoplasm involving the esophagus. "Previous studies reported that in esophageal cancer cells, IGFBP-2 forms a nuclear complex with EGFR and DNA-PKcs following DNA damage." (PMID 38893232, 2024). "Increased expression of IGF1R, IGFBP3, IGFBP4, IGFBP7, and IGFBP8 was reported in human esophageal cancer, while the expression of IGFBP2 and IGFBP6 was reduced." (PMID 32041673, 2020). "Due to the established importance of both the IGF and integrin signaling pathways in esophageal cancer, IGFBP2 would be an ideal therapeutic target in the treatment of EAC." (PMID 26317790, 2015). "In addition, previous research has indicated that IGFBP-2 influences DNA-PKcs in DSB repair (DSBR) in prostate and esophageal cancer cells." (PMID 38893232, 2024).
fragile X syndrome (5 papers, 2019 to 2026). A genetic syndrome caused by mutations in the FMR1 gene which is responsible for the expression of the fragile X mental retardation 1 protein. "In addition, increased release of Igfbp2 reverses the inhibitory effect of neurite growth by blocking BMP signaling in astrocytes of patients with fragile X syndrome and RTT." (PMID 40537021, 2026). "Moreover, the release of insulin-like growth factor-binding protein 2 (Igfbp2), an inhibitor of insulin-like growth factor secretion, has been shown to reverse neurite growth inhibition by blocking bone morphogenetic protein (BMP) signaling in astrocytes associated with fragile X syndrome and RTT." (PMID 40537021, 2026).
lung adenocarcinoma (5 papers, 2013 to 2025). A carcinoma that arises from the lung and is characterized by the presence of malignant glandular epithelial cells. "Next, we are ready to collect early lung adenocarcinoma tissues and detect IGFBP2 expression, and look forward to provide some evidence for the progression of early NSCLC." (PMID 29500455, 2018). "Similarly, in lung cancer, IGFBP2 is found to be overexpressed in the majority of small cell lung carcinomas but reduced in the majority of lung adenocarcinomas." (PMID 25774149, 2015). "Therefore, we inferred that IGFBP2 may exert in early micro-infiltration process of lung adenocarcinoma." (PMID 29500455, 2018). "The IGFBP2 promoter has been shown to be hypermethylated, in a subset of tumors, including 8% of small cell lung carcinomas, >20% of renal cell carcinomas, ~30% squamous cell lung cancers, 40% of colorectal cancers, >70% lung adenocarcinomas, and 75% hepatomas." (PMID 25774149, 2015). "Therefore, IGFBP-2 may offer a novel therapeutic target and serve as an anti-apoptotic biomarker for lung adenocarcinoma." (PMID 23165420, 2013). "For instance, COL5A1 has been implicated in promoting mechanical stress and therapy resistance in lung adenocarcinoma, while COL11A1 activates CAFs through the TGF-β/NF-κB/IGFBP2 signaling axis in various solid tumors." (PMID 40574832, 2025). "Intracellular IGFBP-2 exhibits antiapoptotic properties, which proved that overexpression of IGFBP-2 reduces the expression of caspase-3 in lung adenocarcinoma." (PMID 34728751, 2021).